TNF (tumor necrosis factor)
Diseases named in the same sentence as TNF in open-access papers (continued):
Sharing a sentence is not in itself a finding about the gene and the disease.
depression (continued). "Anti-TNF-α treatment for Crohn’s disease also significantly improved the patient’s DepS, which further proved that TNF-α might lead to depression." (PMID 36615742, 2022). "For instance, an earlier study in patients with treatment-resistant depression showed that the tumor necrosis factor antagonist infliximab reduced depressive symptoms to a greater extent than placebo when baseline CRP levels were above 5 mg/L compared to when CRP levels were below this threshold." (PMID 35566447, 2022). "Similarly, many studies found that TNF-α levels are higher in patients with major depression, bipolar disorder and schizophrenia than in matched-controlled subjects." (PMID 36148246, 2022). "Patients with major depression exhibit significant inflammatory responses, including the increased expression of pro-inflammatory cytokines such as interleukin 6 (IL-6), interleukin 18 (IL-18) and tumor necrosis factor α (TNF-α)." (PMID 35334870, 2022). "Furthermore, trials of cytokine inhibitor use in depression, such as infliximab (anti-TNFα) and sirukumab (anti-IL-6), selectively display efficacy in patients with low- inflammation levels prior to treatment." (PMID 35977923, 2022). "Furthermore, TNF-α, IL-1β, and IL-17 were positively associated with HADS-D score, while high IL-1β, IL-6, and IL-17 correlated with depression occurrence." (PMID 35239774, 2022). "Nonetheless, after 11 months, it is females with depression-like behavior who show an increased concentration of TNF in the prefrontal cortex, whereas in males, this concentration does not differ from the level of control females and between control males and males with a history of NIA." (PMID 36619667, 2022). "Depression leads to an increase in proinflammatory cytokines, tumor necrosis factor-alpha (TNF-α), interleukin-1 (IL-1), and interleukin-6 (IL-6) which stimulate central serotonin neurotransmission and are linked to hypothalamic-pituitary-adrenal overactivity increasing the risk of CVD and MI." (PMID 36237772, 2022). "However, in contrast to these positive results, other studies have cast doubt on the efficacy of selective TNF-α inhibition as a therapeutic strategy for depression." (PMID 36145284, 2022). "Anti-TNF-α compounds were reported as a potential therapeutic strategy for depression." (PMID 36408212, 2022). "Depression in the absence of other diseases has been shown to be associated with increased levels of various pro-inflammatory cytokines, including TNF-α and interleukin." (PMID 35733802, 2022). "For example, a study, using SEM, proposed a model that cortisol (as an indicator of Hypothalamic pituitary adrenal) predicts depression, which predicts circulating pro-inflammatory cytokines (IL-2, IL-6, TNF-α) In patients diagnosed with chronic fatigue syndrome (CFS)." (PMID 36210450, 2022). "This hypothesis is supported by studies reporting increased cerebrospinal fluid levels of the inflammatory markers interleukin (IL)-6, IL-8 and tumor necrosis factor alpha (TNF-α) in patients with ongoing depression." (PMID 36172507, 2022). "Indeed, there is evidence that CRP levels show less variability in individuals with depression and that IL-6, IL-8 and TNF-α levels show less variability in individuals with psychotic disorders." (PMID 36085284, 2022). "The levels of TNF-α and IL-6 were positively correlated with the severity of depression." (PMID 36431060, 2022). "Regulation of TNF-α to normal levels might be considered as an alternative therapy or prophylactic strategy for depression." (PMID 36615742, 2022). "Noteworthy, inflammatory processes are involved in the pathophysiology of depression and microglia dysfunction is considered a key event in depression, with patients showing increased blood concentration of proinflammatory cytokines such as IL-1β, IL-6 and TNF-α." (PMID 36232813, 2022).
depression (continued). "It has also been suggested that depression is an inflammatory disorder characterized by increased levels of proinflammatory cytokines such as tumor necrosis factor (TNF), interleukin-1β (IL-1β), and IL-6 in several brain regions, and similar findings have been reported in experimental studies." (PMID 36185078, 2022). "Although there are no reports of monoclonal antibody use for the treatment of PTSD, multiple studies reported that etanercept (TNF inhibitor), adalimumab (TNF inhibitor), and ustekinumab (IL-12/23 inhibitor) reduced symptoms of depression and anxiety in individuals with psoriasis." (PMID 35927237, 2022). "Our finding of a positive relationship between NfL levels and TNF-α levels may imply that neuroaxonal injury and neuroinflammation synergically contribute to the development of major depressive disorder." (PMID 34637515, 2022). "Furthermore, clinical researches showed that patients with depression had elevated IL-1β, IL-6, and TNF-α levels." (PMID 36578534, 2022). "TNF induce low-grade inflammation, and inflammatory cytokines were the receptor regulators of 5-HT, which were related to the pathogenesis of anxiety and major depression." (PMID 36560929, 2022). "Previous studies have shown that CRP level, mean platelet volume, and the levels of tumor necrosis factor (TNF)-α and cytokines such as interleukin-1 and 6, in peripheral blood were significantly higher in patients with the depressive disorder than in a healthy population." (PMID 35395781, 2022). "Also, numerous studies have shown that patients with major depression have elevated levels of TNF-α and that fluctuation of this pro-inflammatory cytokine (as well as that of IL-6) influences the mood behavior of the affected individuals (for review see." (PMID 34367160, 2021). "The serum TNF-α levels can also assess the severity of depression." (PMID 34479552, 2021). "Besides the functional status, cognitive impairment, and depression severity, 3-nitrotyrosine (3-NT), nitrate/nitrite estimation, and tumor necrosis factor (TNFα) were measured in plasma." (PMID 34557522, 2021). "After remission of depression, patients with BD had elevated IL-4 and TNF." (PMID 33946871, 2021). "This hypothesis about the time course of TNF-α levels in depression could in general explain the inconsistency of TNF-α levels determined in different cohorts of depressed patients investigated thus far." (PMID 34257748, 2021). "Excessive secretion of IL-1β, IL-6, and TNF-α triggers depression-like symptoms." (PMID 33584387, 2021). "TNFα represents a molecule whose role in the onset of depression has been widely demonstrated." (PMID 33397417, 2021). "Therefore, the relation between BDNF, IL-6, TNF-α, and depression severity before, during, and following ECT in severe LLD will be examined." (PMID 34841285, 2021). "In the patient group, TNFα was significantly associated with levels of fatigue (0.22 [0.03 0.41] p = 0.026), but not with pain intensity, depression, or widespreadness of pain in the full regression model." (PMID 34248700, 2021). "Depression can lead to the upregulation of tumor necrosis factor (TNF) and interleukin (IL)-6." (PMID 34439637, 2021). "So, increased TNF-α and IL-1β in the hippocampus in our work may contribute to depression-like behaviors by affecting adult hippocampal neurogenesis." (PMID 34827513, 2021). "On the other hand, elevated peripheral IL and TNF levels were reported in patients with depression." (PMID 34876186, 2021). "The proinflammatory IL-1β and TNF-α cytokines could also interfere with the brain and lead to decreased appetite, sleep disturbance, and depression." (PMID 34200732, 2021). "In addition, compared with UCMS stress mice, LPS stress mice showed stronger expression and release of TNF-α, IL-1 β, and IL-6 in serum and depression-related brain regions (frontal cortex, hippocampus, and striatum)." (PMID 34531719, 2021).
depression (continued). "Importantly, a similar signature of inflammatory changes, including elevated blood levels of interleukin (IL)-6, tumor necrosis factor (TNF)-α, and CRP, was also found in inflammation-associated depression." (PMID 32873895, 2021). "Only five studies could be included into the meta-analysis, where they found TNF-α increased in participants with depression compared to controls." (PMID 34204400, 2021). "IL-6 and TNF-α may play a more important role than other cytokines in the pathogenesis of depression." (PMID 34733143, 2021). "However, orally gavaged or intraperitoneally injected buspirone significantly reduced EC-induced anxiety-/depression-like behaviors, suppressed EC-induced TNF-α and IL-1β expression in the hippocampus." (PMID 33731795, 2021). "There is some evidence that certain SSRI might alleviate depression because of their effects on cytokines such as IL-6 and TNF-α." (PMID 33961667, 2021). "Furthermore, central and peripheral pro-inflammatory cytokines; tumor necrosis factor-alpha (TNF-α), interleukin-6 (IL-6), and interleukin 1β (IL-1β) were reported to have a strong correlation with depression." (PMID 34804417, 2021). "For example, a recent study showed that elevated baseline plasma TNF-α levels in patients with major depression may predict a better improvement in intensity of suicidal thoughts." (PMID 33921721, 2021). "Rethorst and coworkers found a promising correlation between TNF-alpha levels at baseline and depressive symptoms after 12 weeks of AE, hinting at the possibility that patients with high TNF-alpha levels might benefit more from AE in depression treatment." (PMID 33805073, 2021). "Anti-TNF therapy and immunosuppressants can significantly reduce depression in IBD patients, and anti-TNF therapy may reduce anxiety and depressive symptoms by modulating central nervous function and improving cognitive-emotional processing in IBD patients." (PMID 34127024, 2021). "Besides, it also reduced the expression of TNF-α and IL-1β in the hippocampus and serum of depression mice, and inhibited the M1-like activation of microglia." (PMID 34497527, 2021). "However, the TNF-α/BDNF ratio was positively associated with depression severity, and the association of BDNF-level and depression severity depended on the level of TNF-α." (PMID 34841285, 2021). "Notably, increased levels of pro-inflammatory cytokines such as IL-1β, IL-6 and TNF-α were markedly decreased in patients with depression receiving antidepressant treatment." (PMID 34889698, 2021). "Both TNF-α and IL-6 were reported to be involved in the pathogenesis of depression." (PMID 34040528, 2021). "TNF-α and IL-1β are also increased in major depressive, anxiety and other psychiatric disorders." (PMID 34206415, 2021). "In our study, we observed a significant increase in the expression of TNF-α in the CUMS group, suggesting that depression may promote tumor progression through TNF-α." (PMID 34422050, 2021). "Moreover, suicide victims with depression showed higher levels of IL-1β, IL-6 and TNF in postmortem brains, while the receptors for the production of these cytokines, such as Toll-like receptor 3 (TLR3) and TLR4, were also affected." (PMID 34827513, 2021). "Pro-inflammatory markers TNF-α is up regulated under ELS-induced depression." (PMID 34890365, 2021). "Therefore, there have been calls for peripheral blood IL-1β, IL-6, and TNF as biomarkers of depression patients." (PMID 34650925, 2021). "Besides, patients with depression exhibit increased expression of pro-inflammatory cytokines and their receptors (e.g., IL-1, IL-6, TNF) and increased levels of chemokines in peripheral blood and cerebrospinal fluid (CSF)." (PMID 32688365, 2021). "is that increased IL-6 levels in response to ECT induce neuroplastic change and the eventual decrease in IL-6 and TNF-α levels could be related to recovery of depression or to an anti-inflammatory response of ECT." (PMID 34841285, 2021).
depression (continued). "In patients, TNFα was significantly associated with levels of fatigue (p = 0.026), but not with pain intensity or depression." (PMID 34248700, 2021). "In accordance with previously published data, we also aimed at analyzing correlations between improved cardiorespiratory fitness and health-related outcomes such as depression severity and sleep-quality and correlations between TNF-alpha levels at baseline and positive antidepressant effects of AE." (PMID 33805073, 2021). "In addition, Pandey GN found that the expression of TNF-α mRNA and protein in the prefrontal cortex of patients with depression has increased." (PMID 34479552, 2021). "The “usual suspects” associated with depression tend to be elevated interleukins (ILs), interferons (IFNs) and acute phase proteins, including IL-1β, IL-6, IL-2, IFN-γ, tumour necrosis factor alpha (TNF-α) and C-reactive protein (CRP)." (PMID 34816138, 2021). "Animal research also showed that treatment with agomelatine reversed the signs of anxiety and depression, and decreased the cytokines (tumor necrosis factor-α [TNF-α], interleukin 6 [IL-6], and IL-1β), thiobarbituric acid reactive substances, as well as caspase-3 activity." (PMID 34079622, 2021). "In comparison with healthy controls, patients with major depression have higher concentrations of inflammatory cytokines, including tumor necrosis factor (TNF)-α, interleukin (IL)-1β, IL-6, and C-reactive protein (CRP), while lower IL-10 concentration in blood." (PMID 34975477, 2021). "Small sample clinical studies have shown that XPJYD can reduce serum LPS, D-lactic acid, DAO content in patients with depression and then reduce serum IL-6 and TNF-a content, indicating that XPJYD can repair the intestinal mucosal barrier and reduce the inflammatory response to a certain extent." (PMID 34257681, 2021). "Probiotic Lactobacillus plantarum has demonstrated an anti-depressive effect in mice models and adults with depression and is involved in the mitigation of inflammation through downregulation of IL-6 and TNF-α and significant restoration of intestinal permeability and Lactobacillus population." (PMID 34065187, 2021). "Serum TNF-α levels in patients with depression significantly increase." (PMID 34479552, 2021). "Relationship between TNFα and IL-6, respectively, to fatigue, depression and pain intensity." (PMID 34248700, 2021). "Furthermore, they induced TNF-α, IL-1β, and IL-6 expression NF-κB+/Iba1+ cell population in the hippocampus and corticosterone and IL-6 levels in the blood, resulting in anxiety/depression through the regulation of neuroinflammation." (PMID 33731795, 2021). "Thus, IL-6, IL-17, and TNF levels are higher in patients with depression compared with healthy controls." (PMID 34124110, 2021). "Similarly, in salivary samples significant decrease in IL-6 and TNF-α were reported in depressed participants but the levels of cortisol were similar in patients remitted from major depressive disorder when compared to controls." (PMID 35002817, 2021). "Microglial is activated in neuroinflammation with an ameboid feature, which is characterized by enlarged cell bodies and synaptic retraction, contributing to the development of depression and produce pro/anti-inflammatory cytokines such as IL-1β, TNF-α, and IL-650,51." (PMID 34103482, 2021). "In addition, various antidepressants can reduce the level of TNF-α in the peripheral blood of patients with depression." (PMID 34479552, 2021). "However, oral administration of buspirone significantly reduced IS-induced anxiety-/depression-like behaviors and suppressed IL-1β and TNF-α expression and NF-κB+/Iba1+ cell population in the hippocampus." (PMID 33731795, 2021). "Notably, TNF-α seems to have special significance, appearing consistently elevated across all stages of mania and depression." (PMID 34112182, 2021). "Increased IL-1β, IL-10 and TNF levels are present in patients with depression." (PMID 34610039, 2021).
depression (continued). "Both TNF-α and IL-6 were reported to be involved in pathogenesis of depression." (PMID 34867356, 2021). "The results of our PPI network analysis that IL-6 and TNF are the top five targets also confirmed this view, indicating that they may play an important role in the treatment of DM and depression." (PMID 34875999, 2021). "Exposure to stressors including immobilization, antibiotics, or pathogen infection causes anxiety-like behaviors in rodents and induced the expression of proinflammatory cytokines TNF-α, IL-1β, and IL-6 in the hippocampus and colon, resulting in the occurrence of anxiety/depression and colitis." (PMID 33731795, 2021). "Notably, increased peripheral levels of IL-1β, and of IL-1β and IL-6, but unchanged TNF-α, were reported in patients with AD or major depression, respectively." (PMID 34109176, 2021). "Studies related to the observation of a group of adolescents showed that a greater exposure to stressful interpersonal life events was correlated with a significant increase in depression over time, but only in people showing faster TNFα mobilization and interleukin-1β reactivity to social stress." (PMID 33385173, 2021). "This may result in an increased chance of developing post-COVID depression due to longer exposure to the pro-inflammatory effects of TNF-α." (PMID 34575258, 2021). "Furthermore, tumor necrosis factor-α (TNF- α), interleukin-1β (IL-1β), and interleukin-6 (IL-6) measured in the cerebrospinal fluid of MS patients correlate with depression scores." (PMID 34764926, 2021). "SIRT-1 levels are lower in bipolar depression than in euthymia, and TNF-α levels may be lower in depression than in mania." (PMID 34295268, 2021). "Additionally, plasma inflammatory factor levels of IL-6, IFN-γ, and TNF-α were significantly increased in the depression group compared with the healthy ones." (PMID 34650925, 2021). "Regarding TNF-α, in a rat corticosterone-induced depression model, peripheral administration of the TNF-α inhibitor etanercept prevented the loss of newborn neurons, promoted the complexity of the dendritic branching of the new neurons, and recovered hippocampal-dependent memory deficits." (PMID 34298958, 2021). "However, we found a significant interaction between TNF-α and BDNF levels in relation to depression severity, suggesting that the effect of BDNF levels on depression severity depends on the level of TNF-α." (PMID 34841285, 2021). "Depression not only increases the risk of surgery or hospitalization in IBD patients but also reduces postoperative ostomy recovery and affects the effectiveness of anti-TNF therapy in CD patients." (PMID 34127024, 2021). "In addition, plasma TNF levels were positively correlated with the number of failed treatment trials in unmedicated, medically stable patients with major depressive disorders." (PMID 34475376, 2021). "Furthermore, fecal microbiota transplantations suppressed IS-induced TNF-α, IL-1β, and IL-6 expression and NF-κB+/Iba1+ cell population in the hippocampus, resulting in the amelioration of anxiety/depression." (PMID 33731795, 2021). "Recently, several studies have investigated the influence of peripheral proinflammatory cytokines (e.g., IL-6, IL-1β, and TNF-α) on neuronal synaptic plasticity, neurogenesis, and neuromodulation, which play critical roles in the initiation, relapse, and progression of depression." (PMID 33466877, 2021). "Chronically activated microglia, increased cell density and hyper-ramified morphology, and the enhanced release of pro-inflammatory cytokines, e.g., TNF-α, IL-1β, and IL-18, are observed in response to stress, major depression, or AD, leading to disease progression and brain damage." (PMID 34109176, 2021). "A study on depression therapy that used a dose of 150 mg/kg in combination with Escitalopram oxalate tablet to significantly improve clinical symptoms of depression and serum TNF-α levels." (PMID 34666797, 2021).